NLRC5 (NLR family CARD domain containing 5)
Diseases named in the same sentence as NLRC5 in open-access papers (continued):
Sharing a sentence is not in itself a finding about the gene and the disease.
tumor (continued). "DIABLO (permutation test, p < 0.005) identified 15 transcripts in the CD20+ tumor cells (AOIs) to be positively associated with T-cell-rich MCLs, including IL7R, CD47, CD80, CD84 and NLRC5." (PMID 39001353, 2024). "Organoid lines also exhibited somatic mutations in RCC‐related genes which were in concordant with respective tumor including ESPL1, SMARCB1, RAB21, NCOR1, NLRC5, NOTCH2, and FOXA2 mutations." (PMID 38923304, 2024). "In the present study, we firstly examined the expression level of NLRC5 in tumor tissues of 100 HCC patients by immunohistochemistry, and analyzed its prognostic value." (PMID 39132868, 2024). "In the present study, we assessed the expression of NLRC5 by using immunohistochemistry in HCC tumor tissues." (PMID 39132868, 2024). "The findings prove that NLRC5 induces dMMR in EC and promotes tumor proliferative capacity in vitro and in vivo." (PMID 38822039, 2024). "Apparently, normal adjacent to primary tumor presented the weak NLRC5, Beclin 1 and LC3 staining in cervical epithelium layers." (PMID 38961101, 2024). "Paradoxically, previous studies have shown that NLRC5 promotes tumor cell proliferation, migration, and invasion in various cancers, including renal clear cell carcinoma, hepatocellular carcinoma, and gastric cancer." (PMID 38822039, 2024). "Mechanistically, a plethora of tumor related signaling pathways are involved in the regulation of NLRC5 in cancer." (PMID 38961101, 2024). "Researchers believe that NLRC5 plays a key role in tumor MHC-class-I-dependent immune response and CD8+ T cell activation." (PMID 39132868, 2024). "The aim of this study is to evaluate NLRC5 expression in the tumor tissues of HCC patients undergoing surgical treatment, assess its prognostic value, and explore its relationship with critical immune-related molecules within the tumor microenvironment." (PMID 39132868, 2024). "The results suggested that LPS inhibited the ability of NLRC5 in promoting the migration and invasion of tumor cells." (PMID 38822039, 2024). "The last two groups of MAPs likely include inducers and targets of CD8+ T-cell mediated immunity in tumor cells stably expressing NLRC5 that contribute to tumor growth control." (PMID 37108368, 2023). "Restoring NLRC5 expression can be helpful for tumor immunogenicity and the recognition of cancer antigenic peptides." (PMID 37508545, 2023). "Relevant studies have shown that NLRC5 is involved in mediating the immune escape of tumor cells, and activation of NLRC5 is known to inhibit tumor progression by promoting anti-tumor immune response." (PMID 37033937, 2023). "Pro-tumorigenic chemo/cytokines such as IL-6, IL-10, CCL2, and CCL5 were decreased in NLRC5+ tumor-bearing ascites, correlating with significantly decreased frequency of tolerogenic DC2s subsets in this compartment." (PMID 38235131, 2023). "Even though a pro-tumor role of NLRC5 is proposed for certain cancers, this needs to be tested in immune-competent settings." (PMID 37108368, 2023). "OC cells overexpressing NLRC5 exhibited slower tumor growth and resulted in higher recruitment of leukocytes in the TME with lower CD4/CD8 T-cell ratios and increased activation of T cells." (PMID 38235131, 2023). "Six out of 18 chemokines/cytokines assessed were significantly decreased in the ascites from NLRC5+ tumor-bearing mice, including IL-6, IL-10, IL-12, CXCL10, CCL5, and to a greater extent, CCL2." (PMID 38235131, 2023). "Taken together, these results indicate that NLRC5-triggered MHC I expression raises the overall presence of immune cells in the tumor." (PMID 38235131, 2023). "Nonetheless, these findings strengthen the translational potential of NLRC5-SA for restoring tumor immunogenicity and tumor antigen discovery." (PMID 37108368, 2023).
tumor (continued). "Analysis of microarray datasets revealed a correlation between elevated NLRC5 expression and extended survival in OC patients; however, NLRC5 was scarcely detected in the OC tumor microenvironment." (PMID 38235131, 2023). "Remarkably, even in tumor-naïve mice, PBMCs recognized and secreted IFN-γ only in the presence of TAAs derived from NLRC5+ tumor cells, potentially underlining overproduction/presentation of self-peptides recognized by circulating T cells." (PMID 38235131, 2023). "NLRC5-SA induces significant modulation of the MHC-I peptide repertoire in tumor cells that partially overlaps with changes induced by full-length NLRC5." (PMID 37108368, 2023). "Overall, our findings indicate that NLRC5-SA can be exploited in tumor immunotherapy approaches for diverse cancers in two ways." (PMID 37108368, 2023). "To validate our findings, we assessed, at the transcriptional level, NLRC5 and classic HLA I expression in cells from ascites (peritoneal fluid) from OC patient samples from our tumor bank." (PMID 38235131, 2023). "T lymphocytes infiltrating the ascites were less impacted by NLRC5 overexpression than those found in the tumor." (PMID 38235131, 2023). "MHC I expression was confirmed at endpoint by immunofluorescence of tumor samples, validating NLRC5-driven MHC I expression during tumor growth." (PMID 38235131, 2023). "DOK2, GBP4, PSMB9, and NLRC5 were significantly changed according to methylation subgroups, survival, tumor stages, and T categories and were positively correlated, which was validated in the testing group (P < 0.05)." (PMID 36268281, 2022). "Another potential application of NLRC5 in cancer immunotherapy is its possible use for the discovery of immunogenic tumor antigenic peptides." (PMID 33671123, 2021). "And the expression of MHC class I related genes except NLRC5 which was lowest expressed in primary tumor, were similar among primary tumor, regional lymph nodes and distant metastasis." (PMID 33995666, 2021). "Stromal score, immune score, and estimate score, which indicate infiltrating level of stromal cells, immune cells, and tumor purity, respectively, correlated positively with NLRC5 expression in both datasets." (PMID 34307322, 2021). "Contrary to the studies highlighting the role of NLRC5 in reducing tumor growth by eliciting antitumor immunity, several reports suggest a potential role of NLRC5 in promoting cancer growth." (PMID 33671123, 2021). "Can radiation induced NLRC5 can be tuned to allow for improved antigen presentation before tumor cell death?" (PMID 33671123, 2021). "All these studies lend support to the notion that restoration of NLRC5 expression in cancer enhances MHC-I expression in tumor cells leading to efficient antitumor immune response and CTL-mediated killing of tumor cells." (PMID 33671123, 2021). "NLRC5 is an important regulator in antigen presentation and inflammation, and its dysregulation promotes tumor progression." (PMID 34307322, 2021). "NLRC5 activates β-catenin transcription and translation by stimulating the Wnt/β-catenin signaling pathway, thereby promoting tumor development and progression." (PMID 34220868, 2021). "On the other hand, overexpression of NLRC5 in cancer models has demonstrated improved tumor immunogenicity." (PMID 33547395, 2021). "Paradoxically, high NLRC5 expression appeared to favor cancer progression in hepatocellular carcinoma, by stimulating tumor proliferation via the AKT pathway and promoting epithelial-to-mesenchymal transition (EMT) via Wnt/β-catenin signaling." (PMID 34201655, 2021). "In fact, loss-of-function (LOF) alterations in NLRC5 and CIITA were consistent with the loss of MHC class I and class II expression in NPC tumor cells." (PMID 34234122, 2021).
tumor (continued). "For example, patient‐derived tumour cells can be genetically engineered to overexpress NLRC5 in vitro." (PMID 35845006, 2020). "In summary, our data establish NLRC5 as a novel MHC‐I‐related immune evasion mechanism utilised by FL tumours to establish impaired antigenicity." (PMID 35845006, 2020). "In the current study, targeted sequencing in a cohort of 172 FL tumours identified abnormalities in NLRC5 as the most frequent gene abnormality observed in MHC‐I pathway genes." (PMID 35845006, 2020). "Our data indicate that NLRC5 is a novel MHC‐I‐related immune evasion mechanism utilized by FL tumours to impair antigenicity." (PMID 35845006, 2020). "Further research will provide more detailed analysis in different tumor entities and in vivo relevance to establish an eventual role and molecular function of NLRC5 in cell proliferation and cell signaling pathways." (PMID 28261210, 2017). "Data by Rodriguez and colleagues demonstrate the beneficial impact of increasing the activity of NLRC5 in tumor cells in vivo." (PMID 27437103, 2016). "IFN has already shown potential in tumor treatment, and would have the additional benefit of inducing NLRC5 in professional antigen-presenting cells and of lowering the threshold for natural killer (NK) cell activation." (PMID 27437103, 2016). "Increasing NLRC5 expression in tumor cells can thus enhance natural anticancer immunity and immunotherapeutic responses especially in the case of MHC class I low tumors." (PMID 27437103, 2016). "One way of translating these results to human therapy envisages engineering patient-derived tumor cells to overexpress NLRC5 in vitro." (PMID 27437103, 2016). "In any case, NLRC5 expression level strongly correlates with the expression of a number of MHC class I genes in human tumor cell lines (Broad-Novartis Cancer Cell Line Encyclopedia)." (PMID 24319445, 2013). "Single-cell assay for transposase-accessible chromatin sequencing (scATAC-seq) now enables direct, cell-resolved measurement of chromatin accessibility at promoters and enhancers of HLA genes, NLRC5 and interferon-pathway effectors within complex tumor ecosystems." (PMID 41383594, 2025). "Interestingly, the NLRC5‐superactivator (NLRC5‐SA), a smaller fusion protein variant of NLRC5, effectively enhances MHC‐I expression in tumour cells, comparable to full‐length NLRC5." (PMID 40673641, 2025). "Our ongoing studies aim to see whether restoration of NLRC5 and/or use of dsRNA analog such as poly I:C can actually enhance antigen presentation, T cell-mediated tumor cell killing, and sensitivity to ICB in HNSCC models with deficient IFN/STAT1 signaling." (PMID 38231444, 2024). "Moreover, our previous study has suggested that NLRC5 promotes the progression of tumor by inducing the expression of programmed death-ligand 1 (PD-L1) in EC cells." (PMID 38822039, 2024). "Some studies have shown that certain specific mechanisms of NLRC5 depend on its functional regions, but whether the effects of these functional regions are related to the tumor microenvironment is also unclear." (PMID 38961101, 2024). "The results showed that the expression of NLRC5 was significantly associated with patient prognosis in tumor tissues, but not in adjacent non-tumor tissues." (PMID 39132868, 2024). "To examine the possible role for NLRC5 in influencing immune cell infiltration, we performed a deeper analysis of scRNA-seq data to discriminate NLRC5 expression in the malignant cells or immune compartment (CD45+) according to tumor immune infiltration classification." (PMID 38235131, 2023). "Secondly, NLRC5-SA could be exploited for the discovery of tumor antigenic peptides from primary tumor cells and tumor organoid cultures." (PMID 37108368, 2023). "NLRC5-SA promotes tumor growth control similarly to full-length NLRC5." (PMID 37108368, 2023). "We also postulate that LMP1 induced NLRC5 may also upregulate MHC-I for anti-tumor CD8+ T cell responses, which should be examined." (PMID 36632221, 2023).
tumor (continued). "The use of P4 treatment in EBV+ NPCs to upregulate NLRC5 may provide an advantage to enhance anti-tumor immune responses." (PMID 36632221, 2023). "Whole tumor lysates overexpressing NLRC5 could achieve a better antitumoral response and T-cell clonality toward self-peptides that can be exploited in a dendritic cell vaccine delivery." (PMID 38235131, 2023). "Furthermore, quiescent CSCs protect the ability of T cells to recognize and lysis of tumor cells by downregulating NLR family CARD domain containing 5 (NLRC5) trans-activator which belongs to the MHC class I mediated immune responses." (PMID 36810098, 2023). "Therefore, NLRC5 expression acquisition in tumor cells can enhance their MHC-I expression and antigen presentation and put forward antitumor immune response and CTL-mediated destruction." (PMID 37508545, 2023). "Circulating T cells derived from NLRC5-overexpressing tumor-bearing mice showed a greater ability to be activated, producing higher amounts of IFN-γ and displaying higher expression of T-bet and Eomes transcription factors which are known to cooperate to regulate CD8+ T cell effector function." (PMID 38235131, 2023). "Therefore, there is potential for LMP1 as a therapeutic tool to stimulate NLRC5 for enhancing anti-tumor T cell responses in the TME." (PMID 36632221, 2023). "However, in contradiction with the studies above focusing on the antitumor aspects of NLRC5, there are also studies implicating the role of NLRC5 in promoting tumor growth." (PMID 37508545, 2023). "We next tested the association of primary/metastasis-specific downregulation of an MHC class I metagene signature composed of a composite expression of HLA-A, HLA-B, HLA-C, B2M, TAP1, TAP2 and NLRC5 between metastasis and matched primary tumor according to intrinsic subtype." (PMID 36585450, 2023). "NLRC5 was considered a potential immune molecule in antitumor treatment that could be used to improve tumor immunogenicity and restore antitumor immunity." (PMID 36268281, 2022). "It is likely that APCs acquire MHC-I bearing tumor antigenic peptides from NLRC5 expressing B16 cells, presumably via the process of ‘trogocytosis’, and that such ‘cross-dressed’ APCs induce antitumor immune response more efficiently than APCs processing the antigens of parental B16 cells." (PMID 33671123, 2021). "However, immune response elicited by NLRC5-expressing tumor cells can be effective against parental cells bearing low MHC-I." (PMID 33671123, 2021). "However, the strong inhibition of tumor growth that we observed suggests that the STAT3 function in vivo is largely depended on NLRC5." (PMID 33754073, 2021). "Whether NLRC5 deficiency affects MHC-Ib expression in other tissues and cells, and how this would impact NK cell-mediated tumor killing and the development of adaptive antitumor immunity, are questions that need to be addressed." (PMID 33671123, 2021). "Whether tumor cell intrinsic NLRC5 expression is essential, or NLRC5 expression in APCs is sufficient, preventing the emergence of neoplastic clones remains to be addressed." (PMID 33671123, 2021). "Even though NLRC5 overexpression enhances tumor immunogenicity, whether NLRC5-independent MHC-I expression is sufficient for cancer immunosurveillance has not been yet experimentally addressed." (PMID 33671123, 2021). "As the regulator of MHC class I genes, NLRC5 could enable tumor cells to activate CD8+ T cells, and its deficiency would impair tumor cell killing by CD8+ T cells, then promote tumor growth and metastasis." (PMID 34307322, 2021). "A recent study shows that MHC-I expression in tumor cells can be induced independently of NLRC5." (PMID 33671123, 2021).
tumor (continued). "However, knockdown of NLRC5 can weaken the expression of c-Myc and cyclin D1, thereby inhibiting the growth of tumor cells." (PMID 34220868, 2021). "Is NLRC5 essential or dispensable for tumor immune surveillance?" (PMID 33671123, 2021). "Upon subcutaneous transplantation of NLRC5‐expressing cells, recipient mice showed markedly reduced tumour growth demonstrating that NLRC5 could be exploited to elicit antitumour immunity." (PMID 35845006, 2020). "In order to test whether cancer cell upregulation of MHC-I by NLRC5 is sufficient to explain the increased ability of CD8+ T cells to drive tumor clearance, we generated cancer cell lines with constitutively high levels of MHC-I." (PMID 32355214, 2020). "Additionally, overexpression of LMX1A partly rescued the miR‐499a‐5p‐induced tumour‐suppressive effects through elevating the NLRC5 expression." (PMID 31207033, 2019). "NLRC5 could therefore be exploited to restore tumor immunogenicity and to stimulate protective antitumor immunity." (PMID 29394898, 2018). "Perturbations in NLRC5 and PD-L1 gene expression may lead, as a consequence, to a dysregulation of the anti-tumor immune response, which in turn may influence CRC development." (PMID 29408916, 2018). "Indeed, induced expression of NLRC5 was recently correlated with enhanced immunogenicity and reduced tumor progression in a mouse model of melanoma." (PMID 28261210, 2017). "The role of endogenous NLRC5 with regard to tumor progression and immunotherapy efficacy is still unexplored; Nlrc5-knockout mouse models are valuable tools to address these points, in addition to a thorough analysis of NLRC5 transcript levels and somatic mutations in human tumors." (PMID 27437103, 2016). "In addition, the expression of NLRC5 is also influenced by the tumor immune microenvironment." (PMID 38961101, 2024). "Thus, we propose that NLRC5-SA, with its ability to increase tumor immunogenicity and promote tumor growth control, could overcome the limitations of NLRC5-FL for translational immunotherapy applications." (PMID 37108368, 2023). "The relevance of LMP1 to NLRC5 may reinforce the importance of the EBV gene in anti-tumor immunity." (PMID 36632221, 2023). "However, prophylactic cellular vaccination with irradiated ID8s with basal or NLRC5 overexpression did not alter survival of mice upon challenge with parental cells, underlying the absence of immunogenicity of this tumor model." (PMID 38235131, 2023). "Upregulation of NLRC5 in FP may represent a physiological anti-tumor response in sea turtles." (PMID 33717164, 2021). "It is also possible that the different outcomes of NLRC5 may also depend on the tumor type." (PMID 33671123, 2021). "The role of NLRC5 in tumor is controversial and might depend on the specific tumor type." (PMID 34307322, 2021). "Even though arming OV with NLRC5 is a feasible approach that can achieve both tumor cell killing and elicit effective antitumor immunity, a potential caveat of this approach would be cancer cell lysis may precede effective NLRC5-mediated increase in MHC-I expression and tumor antigen presentation." (PMID 33671123, 2021). "Finally, we investigated if NLRC5 aberrations affect NLRC5 protein expression in FL tumours." (PMID 35845006, 2020). "The most downregulated genes contained known tumor suppressors (ZNF831, AKNA, NR4A1, ARHGAP9, ZBTB16) and regulators of immune response (NLRC5, WDFY4, RASGRP2, IKZF1)." (PMID 39794830, 2025). "Among these genes, NLRC5 and PLCB3, known for their involvement in ccRCC progression and tumor immunity, were also identified." (PMID 40740488, 2025). "NLRC5 plays a crucial role in human cancer immunity because of its importance in MHC class I expression with recruitment and activation of tumor killing CD8+ T cells." (PMID 40596738, 2025). "We initially compared the expression of NLRC5 between HCC and adjacent non-tumor tissues through database analysis." (PMID 39132868, 2024).